STK31 (serine/threonine kinase 31)
Synonyms: SgK396; TDRD8
Tractability: No criterion of Open Targets' tractability assessment is met for any kind of drug.
Target class: Kinase; Other protein kinase unique family; Other protein kinase group; Enzyme; Protein Kinase
Gene: Protein-coding gene on chromosome 7 (23,710,203 to 23,832,513, forward strand). Ensembl gene ENSG00000196335.
Gene Ontology:
Molecular function: ATP binding; protein kinase activity; protein serine kinase activity; protein serine/threonine kinase activity
Cellular component: acrosomal vesicle; cytoplasm
Genetic constraint (gnomAD): Loss-of-function variants: 67 observed, 105.39 expected, observed/expected ratio (o/e) 0.64, 90% interval 0.52 to 0.78. The upper end of that interval is the gene's LOEUF score, 0.78, which puts it in group 3 of 6, group 1 being the genes least tolerant of losing a copy. Missense variants: 1,032 observed, 1,076.4 expected, observed/expected ratio (o/e) 0.96, 90% interval 0.91 to 1.01. Synonymous variants: 404 observed, 365.28 expected, observed/expected ratio (o/e) 1.11, 90% interval 1.02 to 1.2.
Homologues: Orthologues: chimpanzee STK31 (99% identical), macaque STK31 (93% identical), dog STK31 (83% identical), rabbit STK31 (83% identical), mouse Stk31 (78% identical), rat Stk31 (78% identical), guinea pig STK31 (73% identical), tropical clawed frog stk31 (43% identical), zebrafish stk31 (24% identical). Paralogues in human: SND1 (15% identical).
Diseases named in the same sentence as STK31 in open-access papers:
STK31 is named in the same sentence as 27 diseases in open-access papers, as found by Europe PMC text mining. Sharing a sentence is not in itself a finding about the gene and the disease. The quoted sentences say what the papers report.
colon cancer (5 papers, 2014 to 2023). "Knockdown of STK31 in colonic cancer cells promotes cell differentiation and thus suppresses tumorigenicity." (PMID 24586802, 2014). "STK31 was also reported to play a critical role to maintain the undifferentiated state of colon cancer cells, and a downregulation of STK31 could significantly suppress cell proliferation both in vitro and vivo studies." (PMID 36424885, 2023). "Moreover, it has been shown that STK31 knockdown lead to a significant suppression of tumorigenicity in colon cancer cells, while STK31 over-expression promotes an undifferentiated CRC status." (PMID 28412729, 2017). "However, Fok and his group subsequently found that STK31 could also regulate colon cancer cell differentiation." (PMID 28422722, 2017).
colorectal cancer (5 papers, 2014 to 2023). A primary or metastatic malignant neoplasm that affects the colon or rectum. "We found a higher relative STK31 expression level in patients with lymph node metastasis, and demonstrated the diagnostic and prognostic potential of STK31 transcripts in colorectal cancer patients." (PMID 28412729, 2017). "Our data suggest that STK31 might be a potential biomarker in detecting, monitoring and predicting the metastatic risk of colorectal cancer." (PMID 28412729, 2017). "In 2008, STK31 was detected by laser microdissection and cDNA microarray in colorectal cancer cells." (PMID 36424885, 2023). "Our findings demonstrated a close relationship between STK31 expression between tumor stage and lymph node metastasis in colorectal cancer, suggesting a potential functional role in tumor progression." (PMID 28412729, 2017). "In Caco2 and SW1116 colorectal cancer cells, STK31 knockdown enhanced cell differentiation capacity, indicating that STK31 maintains low differentiation in colorectal cancer cells." (PMID 28422722, 2017). "Due to the overexpression of STK31 in cancer cell lines and colorectal cancer tissues, the physiological role of STK31 in tumorigenesis was under investigated by ectopically-overexpressed STK31-GFP." (PMID 24667656, 2014). "Here, we demonstrate that STK31 is overexpressed in many human colorectal cancer cell lines and tissues." (PMID 24667656, 2014). "Human STK31 was reported to be expressed in gastrointestinal cancers, including esophageal, gastric, colonic and colorectal cancers." (PMID 24586802, 2014). "The expression of STK31 mRNA was further evaluated in many colorectal cancer cells compared with AZ521." (PMID 24667656, 2014). "In addition, STK31 has also been detected in gastric cancer, colorectal cancer, cervical cancer, and lung cancer." (PMID 36424885, 2023). "Except for colorectal cancer, STK31 is also abnormally expressed in lung cancer." (PMID 36424885, 2023). "Studies investigating STK31 in cancers mostly focus on colorectal cancers before." (PMID 36424885, 2023). "Recently, STK31 was found to be a cancer-testis antigen (CTA) overexpressed in colorectal cancers." (PMID 24667656, 2014). "STK31 overexpression in clinical colorectal cancer specimens has previously been reported." (PMID 24667656, 2014). "Moreover, STK31 has been detected in colorectal cancer and is activated by demethylation." (PMID 28422722, 2017).
cervical cancer (3 papers, 2016 to 2020). A primary or metastatic malignant neoplasm involving the cervix. "STK31 is a new potential therapeutic target in cervical cancer, especially in HPV16/18-positive cervical tumors." (PMID 32328088, 2020).
lymph node metastasis (3 papers, 2016 to 2018). "Relative STK31 expression level was significantly higher in patients with lymph node metastasis." (PMID 28412729, 2017). "STK31 expression in primary tumor samples of patients with lymph node metastasis was significantly higher than in those without metastasis." (PMID 28412729, 2017).
pancreatic cancer (3 papers, 2017 to 2023). "To evaluate the effect of methylation on STK31 expression, we applied MethylTarget to detect the methylation level in 27 pancreatic cancer tissue samples." (PMID 36424885, 2023). "CCK‐8, EDU, and clone formation assays were conducted to investigate the effect of STK31 on pancreatic cancer cell lines." (PMID 36424885, 2023). "We aimed to identify STK31 as a cancer-testis (CT) gene and to explore its potential clinical value, regulatory mechanisms, and gene network in pancreatic cancer (PC)." (PMID 28422722, 2017). "In addition to the analysis in TCGA database, we also confirmed the relationship between the expression of miR‐543 and gene STK31 in 50 pancreatic cancer tissues from our Pancreas Biobank." (PMID 33128354, 2020). "The expression of STK31 was detected in hTERT‐HPNE cell line and six pancreatic cancer cell lines (Capan‐2, BXPC‐3, CFPAC‐1, MIA PaCa‐2, COLO‐357, and PANC‐1) by qRT‐PCR and western blot." (PMID 36424885, 2023).
breast carcinoma (2 papers, 2020 to 2024). "Furthermore, we tested the expression of FZD2, SFRP2, STK31, and LALBA proteins in canine mammary (CF41 and P114) and human breast cancer cells lines (HCC1500, T47D, DCIS.com, MDA231, and MCF7)." (PMID 32053966, 2020).
testis (2 papers, 2017 to 2023). "The PPI network predicted that STK31 was physically associated with the PIWI (originally P-element Induced WImpy testis in Drosophila) and Tudor families." (PMID 28422722, 2017). "STK31 has been identified as a cancer‐testis (CT) gene, but its function in PC has not been elucidated well." (PMID 36424885, 2023).
cervical tumors (1 paper, 2016). "The methylation statuses and expressions of STK31 were verified in the cervical tumor samples at different stages." (PMID 27044426, 2016). "Herein, we detected methylation status of the STK31 gene in cervical tumors and explored its interaction with HPV16 or/and HPV18 (HPV16/18) infection." (PMID 27044426, 2016). "Our results found that CIN3 represents a more advanced stage of intraepithelial neoplasia than CIN2, and the difference in STK31 methylation between CIN2 and CIN3 may be due to the different stages of the cervical tumors." (PMID 27044426, 2016). "The restoration of STK31 expression by the demethylating agent 5-aza-dC in the C33A and HT-3 HPV-negative CC cell also supports the epigenetic role of STK31 in the etiology of cervical tumors." (PMID 27044426, 2016).
cyst (1 paper, 2025). A sac-like closed membranous structure that may be empty or contain fluid or amorphous material. "The targeted knockdown of Sub1 and Stk31 in vitro resulted in a marked decrease in ovarian germ cell numbers, alongside disruptions in cyst breakdown and follicular assembly." (PMID 40332359, 2025). "In contrast, Stk31-RNAi reduced the number of primordial follicles but did not affect the follicle-to-cyst ratio." (PMID 40332359, 2025).
gastric adenocarcinoma (1 paper, 2014). "Among these, which originated from different tissues, AZ521, a gastric adenocarcinoma, showed the highest STK31 mRNA expression." (PMID 24667656, 2014).
gastric cancer (1 paper, 2014). A primary or metastatic malignant neoplasm involving the stomach. "STK31 mutations were also identified by targeted deep sequencing of kinomes in gastric cancers." (PMID 24667656, 2014). "In addition, STK31 showed the highest expression level in a gastric cancer cell line, AZ521." (PMID 24667656, 2014).
glioblastoma (1 paper, 2022). The most malignant astrocytic tumor (WHO grade IV). "One glioblastoma exhibited only a gain for STK31 on 7p15.3 and GLI3 on 7p14.1." (PMID 35361262, 2022).
lung carcinoma (1 paper, 2023). "STK31 was reported to promote cell proliferation in lung cancer cells by the Wnt/β‐catenin signaling pathway and positive feedback regulation of c‐myc." (PMID 36424885, 2023).
Obesity (1 paper, 2020). Accumulation of substantial excess body fat. "Obesity group also showed a lower mutation frequency of PLCG2, STK31, ADGB, and so on." (PMID 33197880, 2020).
rectal tumors (1 paper, 2019). "CYT-high rectal tumors on the other hand, had recurrent deletions at loci 3p21.31 (RHOA), 5q22.2 (APC), 10q26.2 (MGMT), 14q32.2 (AKT1, EIF5, YY1), 18q21.2 (SMAD4, MAPK4), and a single amplification in 7p15.3 (STK31)." (PMID 31429779, 2019).
cancer (10 papers, 2014 to 2025). A tumor composed of atypical neoplastic, often pleomorphic cells that invade other tissues. "The present study shows that an overexpression of STK31 increases cell migration and invasiveness, while the knockdown expression of STK31 causes mitotic catastrophe and apoptosis in cancer cells." (PMID 24667656, 2014). "In cancer, STK31 expression is found to be upregulated by promoter hypomethylation, which in turn is a predicted driver of cancer cell migration and invasion." (PMID 40431173, 2025). "Among the 148 dark kinases included in our analysis, PKMYT1 (in 17 cancers), Mitogen-Activated Protein Kinase 15 (MAPK15) in nine cancers, CaM Kinase Like Vesicle Associated (CAMKV) in 8 cancers), PNCK and STK31 (in seven cancers) were commonly upregulated." (PMID 33801837, 2021). "Among these, the genes PKMYT1, PNCK, BRSK2, ERN2, and STK31 were significant in survival in five or more cancers." (PMID 33801837, 2021). "On the other hand, cancer STK31, a cancer-testis antigen (CTA), plays crucial roles in human cancer through regulation of the cell cycle, and its over-expression increases cell migration and invasiveness, whereas its depletion induces apoptosis." (PMID 32053966, 2020). "Ectopically-expressed, STK31 increases cell migration and invasiveness of human somatic cancer cells, whereas endogenous STK31 knockdown results in microtubule assembly defects that prolong the duration of mitosis and triggers apoptosis." (PMID 28412729, 2017). "The predicted oncogene STK31, in the top 20 oncogene candidates with a total oncogene score of 20 across the 11 cancer types, is a largely uncharacterized protein kinase." (PMID 27321817, 2016). "STK31 is one of the novel cancer/testis (CT) genes, and the expression of STK31 has been proven to be regulated by the methylation status of its promoter." (PMID 27044426, 2016). "We retrieve the majority of known cancer genes but also new candidates such as STK31 and MSRA with very high confidence." (PMID 27321817, 2016). "In the current study, real time PCR showed a differential expression pattern of STK31 in various human cancer cell lines." (PMID 24667656, 2014). "Serine/threonine kinase 31 (STK31) is one of the novel cancer/testis antigens for which its biological functions remain largely unclear." (PMID 24667656, 2014). "To gain insights into the physiological role of STK31 in cancer cells, we examined the subcellular localization of STK31." (PMID 24667656, 2014). "Taken together, our results suggest that the aberrant expression of STK31 contributes to tumorigenicity in somatic cancer cells." (PMID 24667656, 2014). "In order to further investigate the physiological roles of STK31 in somatic cancer cells, specific STK31 monoclonal (1G10) and polyclonal (19717) antibodies were generated against different human STK31 peptides (upper)." (PMID 24667656, 2014). "Molecular targeting treatment has evolved along with better understanding of the mechanisms of cancer, and STK31 may be a good molecular therapeutic target in PC." (PMID 28422722, 2017). "Moreover, STK31 expression levels in primary cancer tissues of metastatic patients were significantly higher than in ANCTs and in lymph nodes, both at mRNA and protein level." (PMID 28412729, 2017). "The serine–threonine kinase 31 (STK31) gene is a novel cancer testis (CT) antigen." (PMID 28412729, 2017). "STK31 gene of which the expression has been proven to be regulated by the methylation status of its promoter, is one of the novel cancer/testis (CT) genes and plays important roles in human cancers." (PMID 27044426, 2016). "The results have demonstrated that the STK31 gene play crucial roles in human cancers." (PMID 27044426, 2016). "STK31 might serve as a potential target for cancer treatment given that inhibitory compounds targeting cell cycle kinases such as Polo-like kinase 1, Aurora-A and Aurora-B have been quite successful in treating cancers." (PMID 24667656, 2014).
cancer (continued). "We further asked whether depletion of STK31 induces the same effect on mitotic progression in cancer cells." (PMID 24667656, 2014). "Here, we investigate the involvement and physiological role of STK31 in cancer development." (PMID 24667656, 2014). "STK31 could promote cancer progression by facilitating cell proliferation, migration, and invasion." (PMID 36424885, 2023). "Other less understudied commonly upregulated kinases that were frequently found to be significant in survival (≥5 cancers) included the BRSK2, ERN2, PNCK, and STK31 kinases." (PMID 33801837, 2021).
tumor (8 papers, 2014 to 2020). "Our data revealed that, as a member of the CT gene family that encodes unique class of tumor-associated antigens in various malignancies, STK31 is closely related with CRC metastasis." (PMID 28412729, 2017). "High STK31 levels in the primary tumor may be prognostic for high risk of metastasis and correlate with an increased patient mortality, rendering it a potential prognostic factor, biological marker of tumor invasiveness and therapeutic target." (PMID 28412729, 2017). "In our study we aimed to analyze the correlation between STK31 expression patterns and metastasization, tumor stage and grade in CRC patients." (PMID 28412729, 2017). "Measurements of mRNA and STK31 protein levels in tumor cells with high and low metastatic potential by RT-PCR, immunohistochemistry analysis and flow cytometry are warranted." (PMID 28412729, 2017). "STK31 expression was observed in membrane of tumor cells after immunohistological staining." (PMID 28412729, 2017). "Whether STK31 is expressed is related to the pathologic stage, new neoplasm status, and prognosis of PC, which might be a new means of aiding clinical diagnosis and estimating the degree of severity." (PMID 28422722, 2017). "Furthermore, our Stk31 mutant mice will be useful for genetically testing the tumor-suppressing activity of STK31 in gastrointestinal cancer mouse models." (PMID 24586802, 2014). "In addition, the kinase domain in STK31 is required for its tumor-suppressing activity." (PMID 24586802, 2014). "Consistently with the mRNA expression patterns, STK31 protein expression levels in tumor tissues of non-metastatic patients were much lower." (PMID 28412729, 2017). "Interestingly, STK31 expression was significantly higher in patients with new neoplasm compared with patients without new neoplasm (P = 0.046)." (PMID 28422722, 2017).
STK31 also shares sentences with these, for which no sentence is quoted: Anxiety (1 paper); depression (1); fibromyalgia (1); gallbladder cancer (1); infection (1); insomnia (1); intraepithelial neoplasia (1); prostate carcinoma (1); psychiatric disorder (1); schizophrenia (1).